SNORA26 (small nucleolar RNA, H/ACA box 26)
Synonyms: HBI-6
Gene: Small nucleolar RNA gene on chromosome 4 (52,713,249 to 52,713,370, forward strand). Ensembl gene ENSG00000212588.
Gene Ontology:
Biological process: RNA processing
Cellular component: nucleolus
Homologues: Orthologues: chimpanzee SNORA26 (100% identical), macaque SNORA26 (97% identical), rat LOC120099519 (82% identical), rat LOC120094013 (69% identical).
Diseases named in the same sentence as SNORA26 in open-access papers:
SNORA26 is named in the same sentence as 4 diseases in open-access papers, as found by Europe PMC text mining. Sharing a sentence is not in itself a finding about the gene and the disease. The quoted sentences say what the papers report.
colon cancers (1 paper, 2023). "SNORA26 is a small noncoding RNA that has been shown to act as an oncogene in colon cancers as well as other digestive cancers." (PMID 37873786, 2023).
melanoma (1 paper, 2025). A malignant, usually aggressive tumor composed of atypical, neoplastic melanocytes. "siRNA mediated depletion of DANCR targets the mature processed lncRNA transcript and did not affect the levels of SNORA26 suggesting that the embedded small RNAs do not play a significant role in controlling proliferation and migration in melanoma." (PMID 41336739, 2025). "DANCR depletion using siRNA did not affect expression of the embedded SNORA26 gene in melanoma cells, suggesting that the mature DANCR transcript is responsible for regulating these phenotypic changes." (PMID 41336739, 2025).
cancer (2 papers, 2014 to 2020). A tumor composed of atypical neoplastic, often pleomorphic cells that invade other tissues. "Functional enrichment suggest that the co‐expressed genes of SNORA26 can be significantly enriched into Rap1 signaling pathway, pathways in cancer, Hippo signaling pathway, MAPK signaling pathway, sphingolipid signaling pathway, TGF‐β signaling pathway and Wnt signaling pathway." (PMID 32780509, 2020). "It generates miR-4449 and SNORA26 and is downregulated during differentiation, hence upregulated DANCR might contribute to cancer by maintaining a pro-proliferative state." (PMID 25587025, 2014).
SNORA26 also shares sentences with these, for which no sentence is quoted: cannabis dependence (1 paper).